PIP5K1C (phosphatidylinositol-4-phosphate 5-kinase type 1 gamma)
Description:
Catalyzes the phosphorylation of phosphatidylinositol 4-phosphate (PtdIns(4)P/PI4P) to form phosphatidylinositol 4,5-bisphosphate (PtdIns(4,5)P2/PIP2), a lipid second messenger that regulates several cellular processes such as signal transduction, vesicle trafficking, actin cytoskeleton dynamics, cell adhesion, and cell motility. PtdIns(4,5)P2 can directly act as a second messenger or can be utilized as a precursor to generate other second messengers: inositol 1,4,5-trisphosphate (IP3), diacylglycerol (DAG) or phosphatidylinositol-3,4,5-trisphosphate (PtdIns(3,4,5)P3/PIP3) (Probable). PIP5K1A-mediated phosphorylation of PtdIns(4)P is the predominant pathway for PtdIns(4,5)P2 synthesis (By similarity). Together with PIP5K1A, is required for phagocytosis, both enzymes regulating different types of actin remodeling at sequential steps (By similarity). Promotes particle attachment by generating the pool of PtdIns(4,5)P2 that induces controlled actin depolymerization to facilitate Fc-gamma-R clustering. Mediates RAC1-dependent reorganization of actin filaments. Required for synaptic vesicle transport (By similarity). Controls the plasma membrane pool of PtdIns(4,5)P2 implicated in synaptic vesicle endocytosis and exocytosis. Plays a role in endocytosis mediated by clathrin and AP-2 (adaptor protein complex 2). Required for clathrin-coated pits assembly at the synapse. Participates in cell junction assembly. Modulates adherens junctions formation by facilitating CDH1/cadherin trafficking. Required for focal adhesion dynamics. Modulates the targeting of talins (TLN1 and TLN2) to the plasma membrane and their efficient assembly into focal adhesions. Regulates the interaction between talins (TLN1 and TLN2) and beta-integrins. Required for uropodium formation and retraction of the cell rear during directed migration (By similarity). Has a role in growth factor-stimulated directional cell migration and adhesion (By similarity). Required for talin assembly into nascent adhesions forming at the leading edge toward the direction of the growth factor. Negative regulator of T-cell activation and adhesion (By similarity). Negatively regulates integrin alpha-L/beta-2 (LFA-1) polarization and adhesion induced by T-cell receptor (By similarity). Together with PIP5K1A has a role during embryogenesis and together with PIP5K1B may have a role immediately after birth (By similarity).
Synonyms: KIAA0589; PIP5Kgamma; LCCS3; PIP5K-GAMMA; PIP5K1-gamma
Tractability: Small molecule: a high-quality ligand is known; it belongs to a druggable protein family. Antibody: UniProt places it where antibodies can reach, with medium confidence; its Gene Ontology location is reachable by antibodies, with medium confidence. PROTAC: ubiquitination databases record sites on it; its protein half-life has been measured; a small molecule that binds it is known.
Target class: Enzyme; Transferase
Safety:
Unwanted effects reported when the protein is acted on. In parentheses: how it was acted on, where the effect was seen, and who reports it.
alcoholism (source: ClinPGx)
Gene: Protein-coding gene on chromosome 19 (3,630,181 to 3,700,487, reverse strand). Ensembl gene ENSG00000186111.
Subcellular location: Cell membrane; Endomembrane system; Cytoplasm; Cell junction, focal adhesion; Cell junction, adherens junction; Cell projection, ruffle membrane; Cell projection, phagocytic cup; Cell projection, uropodium; Cytoplasm (Isoform 2); Nucleus
Subcellular location (Human Protein Atlas): Nucleoplasm; Cytosol
Pathways (Reactome):
Cell-Cell communication: Regulation of CDH1 posttranslational processing and trafficking to plasma membrane
Developmental Biology: SEMA3A-Plexin repulsion signaling by inhibiting Integrin adhesion
Metabolism: Synthesis of PIPs at the plasma membrane
Signal Transduction: PI5P, PP2A and IER3 Regulate PI3K/AKT Signaling
Vesicle-mediated transport: Clathrin-mediated endocytosis
Gene Ontology:
Molecular function: 1-phosphatidylinositol-4-phosphate 5-kinase activity; protein binding; phosphatidylinositol kinase activity
Biological process: actin cytoskeleton organization; adherens junction assembly; cell-cell adhesion; clathrin-dependent endocytosis; membrane organization; neutrophil chemotaxis; phagocytosis; phosphatidylinositol biosynthetic process; phosphatidylinositol phosphate biosynthetic process; regulation of phosphatidylinositol 3-kinase/protein kinase B signal transduction; synaptic vesicle endocytosis; synaptic vesicle exocytosis; phosphatidylinositol metabolic process; regulation of postsynaptic neurotransmitter receptor internalization; regulation of synaptic vesicle endocytosis
Cellular component: cytosol; endosome membrane; nucleoplasm; cytoplasm; endomembrane system; focal adhesion; uropod; adherens junction; glutamatergic synapse; nucleus; phagocytic cup; plasma membrane; postsynaptic density; presynapse; ruffle membrane
Genetic constraint (gnomAD): Loss-of-function variants: 43 observed, 73.72 expected, observed/expected ratio (o/e) 0.58, 90% interval 0.46 to 0.75. The upper end of that interval is the gene's LOEUF score, 0.75, which puts it in group 3 of 6, group 1 being the genes least tolerant of losing a copy. Missense variants: 752 observed, 935.38 expected, observed/expected ratio (o/e) 0.8, 90% interval 0.76 to 0.85. Synonymous variants: 498 observed, 420.66 expected, observed/expected ratio (o/e) 1.18, 90% interval 1.1 to 1.27.
Gene-disease validity (ClinGen):
ClinGen rates the evidence that PIP5K1C causes each of these diseases.
PIP5K1C-related neurodevelopmental disorder (autosomal dominant): Strong. Any neurodevelopmental disorder in which the cause of the disease is a monoallelic gain-of-function variation in the PIP5K1C gene leading to increased levels of phosphatidylinositol 4,5 bisphosphate.
Homologues: Orthologues: chimpanzee PIP5K1C (97% identical), dog PIP5K1C (93% identical), guinea pig PIP5K1C (92% identical), pig PIP5K1C (91% identical), mouse Pip5k1c (90% identical), rat Pip5k1c (90% identical), macaque PIP5K1C (90% identical), tropical clawed frog pip5k1c (77% identical), zebrafish pip5k1ca (73% identical), zebrafish pip5k1cb (69% identical). Paralogues in human: PIP5K1A (53% identical), PIP5K1B (51% identical), PIP4K2B (19% identical), PIP4K2C (19% identical), PIP4K2A (18% identical), PIP5KL1 (15% identical).
Diseases named in the same sentence as PIP5K1C in open-access papers:
PIP5K1C is named in the same sentence as 21 diseases in open-access papers, as found by Europe PMC text mining. Sharing a sentence is not in itself a finding about the gene and the disease. The quoted sentences say what the papers report.
breast carcinoma (7 papers, 2014 to 2024). "High PIP5K1C protein levels were associated with a poor prognosis in a breast cancer cohort including all subtypes (log-rank test; p = 0.0097; HR = 3.72; confidence interval 1.28–10.8)." (PMID 37803350, 2023). "Further highlighting the oncogenic role of PIP5K1C, we discovered PIP5K1C to show higher expression in breast cancer tissue than in healthy adjacent tissue and to be associated with worse patient survival, which was also reported by one of the discussed studies." (PMID 37803350, 2023). "HECTD1 ubiquitinates phosphatidylinositol-4-phosphate 5-kinase type 1 gamma (PIP5K1C) at lysine 97 resulting in PIP5K1C degradation, consequently leading to focal adhesions dynamics and cell migration in breast cancer cells." (PMID 32787954, 2020). "Furthermore, knockout of PIP5K1C in 4T1 breast cancer cells showed a noteworthy reduction in tumor progression and metastasis." (PMID 37010714, 2023). "Next, we tested if PIP5K1C protein expression is altered during progression of breast cancer." (PMID 30555634, 2018). "Moreover, the expression status of PIP5K1C was unchanged in breast cancer patient samples and cell lines, and PIP5K1C expression seems not to be indicative of distant metastases-free survival." (PMID 30555634, 2018). "Other genes, including ATP5A, BCR, FGFR4, PDPK1, PIP5K1C, RIOK3, and SRC, also act to regulate TRAIL-induced apoptosis, but their potential to overcome resistance to TRAIL-induced cytotoxicity when inhibited may be more context specific (that is, in a more-restricted subset of breast cancer cells)." (PMID 24745479, 2014).
Obesity (2 papers, 2022 to 2024). Accumulation of substantial excess body fat. "Deletion of PIP5K1c in adipocytes significantly alleviated high fat diet (HFD)-induced obesity, hyperlipidaemia, hepatic steatosis, and insulin resistance." (PMID 34996482, 2022). "Together, these data indicate that PIP5K1c could be a novel potential target for regulating fat accumulation, which could provide novel insight into the treatment of obesity." (PMID 34996482, 2022). "However, there is no direct evidence to report the role of PIP5K1c in adipocytes to regulate adipose tissue homeostasis and obesity-related diseases." (PMID 34996482, 2022).
Alzheimer disease (1 paper, 2023). A progressive, neurodegenerative disease characterized by loss of function and death of nerve cells in several areas of the brain leading to loss of cognitive function such as memory and language. "And the results confirmed that there was a close connection among HSPB1, PIP5K1C and five key genes in pathway of Alzheimer’s disease (AD)." (PMID 37010714, 2023).
cerebral infarction (1 paper, 2025). An ischemic condition of the brain, producing a persistent focal neurological deficit in the area of distribution of the cerebral arteries. "We further analyzed the expression differences of Pip5k1c, Nlgn2, Fzd2, Cd86, Agpat1, and Degs2 between the cerebral infarction at 3, 6, and 12 h and the control group." (PMID 40520774, 2025). "The AUC values of Pip5k1c, Nlgn2, Fzd2, Cd86, Agpat1, and Degs2 were all 1, suggesting that Pip5k1c, Nlgn2, Fzd2, Cd86, Agpat1, and Degs2 have good sensitivity and specificity for the diagnosis of cerebral infarction." (PMID 40520774, 2025).
cutaneous melanoma (1 paper, 2025). A primary melanoma arising from atypical melanocytes in the skin. "Furthermore, genetic variants in PIP5K1C and MVB12B, components of the endosomal pathway, have been identified as novel prognostic markers for cutaneous melanoma-specific survival." (PMID 40746552, 2025).
Hypertension (1 paper, 2023). The presence of chronic increased pressure in the systemic arterial system. "However, the mechanism of other genes, such as TXNL1P1, PIP5K1C, MIR3147, and SLC47A1, underlining hypertension requires further investigation." (PMID 36869404, 2023).
ischemic stroke (1 paper, 2025). A stroke disorder caused by obstruction of blood flow to the brain, due to thrombotic (local blood clot formation) or embolic (due to a blood clot or other material traveling from another site) event. "Single-gene GSEA revealed that the identified signature genes (Pip5k1c, Nlgn2, Fzd2, Cd86, Agpat1, and Degs2) converge on neuroinflammatory and apoptotic pathways critical in ischemic stroke pathogenesis." (PMID 40520774, 2025). "The results demonstrated that, in comparison to the control group, the expression of Pip5k1c, Nlgn2, Fzd2, Cd86, Agpat1, and Degs2 showed a downward trend with an increase in the onset time of ischemic stroke, and the decrease was most significant in the MCAO_12 h group (p < 0.01)." (PMID 40520774, 2025).
pancreatic adenocarcinoma (1 paper, 2023). "We identified seven prognostic genes (MET, DYNLL2, CDK1, TNFSF10, PIP5K1C, MSLN, GKN1) and validated that their related proteins, such as EGFR and MMP2, have a significant impact on the prognosis of pancreatic adenocarcinoma." (PMID 37370756, 2023). "Compared with normal tissues, the expression levels of MET, DYNLL2, CDK1, TNFSF10, PIP5K1C, MSLN, and GKN1 were significantly increased in pancreatic adenocarcinoma cells (p < 0.05)." (PMID 37370756, 2023). "No study has confirmed that DYNLL2 and PIP5K1C are prognostic protective gene for pancreatic adenocarcinoma, and this study is the first to do so." (PMID 37370756, 2023).
schizophrenia (1 paper, 2021). A major psychotic disorder characterized by abnormalities in the perception or expression of reality. "PIK4CA expression was lower, whereas Akt expression was higher, in the PFC of schizophrenia patients than in that of controls; PIP5K1C, PTEN, and GSK3β expression was not different." (PMID 34361045, 2021).
Sepsis (1 paper, 2025). Sepsis is defined as life-threatening organ dysfunction caused by a dysregulated host response to infection. "Ultimately, 8 key genes were identified: CD160, HELB, ING4, PIP5K1C, SRPRA (HR < 1); and CDCA7, FAM3A, PPP1R15A (HR > 1), and the hub genes showed apparent differences in expression between alive and dead sepsis patients." (PMID 40612938, 2025). "A lactylation-based prognostic model was developed, comprising eight key genes (CD160, HELB, ING4, PIP5K1C, SRPRA, CDCA7, FAM3A, PPP1R15A), and demonstrated strong predictive performance for sepsis outcomes (AUC = 0.78 in the training cohort; AUC = 0.73 in the validation cohort)." (PMID 40612938, 2025).
cancer (6 papers, 2016 to 2024). A tumor composed of atypical neoplastic, often pleomorphic cells that invade other tissues. "Successful application of PIKFYVE inhibitors will require a comprehensive understanding of the pathways regulated by these inhibitors, their secondary targets, and the ability to identify PIP5K1C phosphoinositide kinase deficient cancers." (PMID 36803256, 2023). "Most autophagy-dependent cancers are PIKFYVE-dependent, and their dependency can be related to a intracellular deficiency in PIP5K1C protein." (PMID 38994949, 2024). "ARHGAP26 and FAM53B were found associated with five cancer types, and PIP5K1C, FBP1, and CUL9 were found to be associated with four cancer types." (PMID 37187613, 2023). "Of the 33 patient derived cancers for which RNA levels have been quantified, 14 of them have significantly less PIP5K1C RNA than their paired normal tissues, suggesting that a significant fraction of cancers will respond to treatment with PIKFYVE inhibitors due to a deficiency of PIP5K1C protein." (PMID 38994949, 2024).
tumor (3 papers, 2023). "In order to evaluate whether targeting PIP5K1C can explain the tumor-suppressive phenotype of miR-4649-5p overexpression, we investigated the effect of siRNA-mediated PIP5K1C knockdown on TNBC cell growth." (PMID 37803350, 2023). "Lastly, the EHD2, CTIF, FBXO32, PIP5K1C, and AHNAK genes were found to be co-expressed in the adjacent healthy tissue and tumor tissue groups." (PMID 37365287, 2023).
PIP5K1C also shares sentences with these, for which no sentence is quoted: ciliopathies (1 paper); colorectal cancer (1); Hepatic steatosis (1); Insulin resistance (1); invasive breast carcinoma (1); metabolic disease (1); metabolic syndrome (1); respiratory failure (1); type 2 diabetes (1).